ATP7B (ATPase copper transporting beta)
Description:
Copper ion transmembrane transporter involved in the export of copper out of the cells. It is involved in copper homeostasis in the liver, where it ensures the efflux of copper from hepatocytes into the bile in response to copper overload.
Synonyms: PWD; WC1; WND; WD
Tractability: Small molecule: a structure with a bound ligand is known; it has a high-quality binding pocket. Antibody: its Gene Ontology location is reachable by antibodies, with high confidence; UniProt predicts a signal peptide or a membrane-spanning region. PROTAC: ubiquitination databases record sites on it; its protein half-life has been measured.
Safety:
Unwanted effects reported when the protein is acted on. In parentheses: how it was acted on, where the effect was seen, and who reports it.
gastrointestinal toxicity (source: ClinPGx)
Gene: Protein-coding gene on chromosome 13 (51,930,436 to 52,012,166, reverse strand). Ensembl gene ENSG00000123191.
Subcellular location: Golgi apparatus, trans-Golgi network membrane; Late endosome; Golgi apparatus membrane (Isoform 1); Cytoplasm (Isoform 2); Mitochondrion (WND/140 kDa)
Subcellular location (Human Protein Atlas): Golgi apparatus
Pathways (Reactome):
Transport of small molecules: Ion transport by P-type ATPases
Gene Ontology:
Molecular function: ATP binding; copper ion binding; copper ion transmembrane transporter activity; P-type monovalent copper transporter activity; protein binding; ATP hydrolysis activity; ATPase-coupled monoatomic cation transmembrane transporter activity; metal ion binding; nucleotide binding
Biological process: cellular detoxification of copper ion; copper ion transport; response to copper ion; copper ion export; copper ion import; intracellular copper ion homeostasis; monoatomic ion transmembrane transport; xenobiotic detoxification by transmembrane export across the plasma membrane; monoatomic cation transport
Cellular component: basolateral plasma membrane; cytoplasm; cytoplasmic vesicle; Golgi apparatus; Golgi membrane; late endosome; membrane; mitochondrion; perinuclear region of cytoplasm; trans-Golgi network; trans-Golgi network membrane; plasma membrane
Genetic constraint (gnomAD): Loss-of-function variants: 115 observed, 126.31 expected, observed/expected ratio (o/e) 0.91, 90% interval 0.78 to 1.06. The upper end of that interval is the gene's LOEUF score, 1.06, which puts it in group 4 of 6, group 1 being the genes least tolerant of losing a copy. Missense variants: 1,867 observed, 1,968.6 expected, observed/expected ratio (o/e) 0.95, 90% interval 0.91 to 0.99. Synonymous variants: 777 observed, 767.76 expected, observed/expected ratio (o/e) 1.01, 90% interval 0.95 to 1.07.
Gene-disease validity (ClinGen):
ClinGen rates the evidence that ATP7B causes each of these diseases.
Wilson disease (autosomal recessive): Definitive. A very rare inherited multisystemic disease presenting non-specific neurological, hepatic, psychiatric or osseo-muscular manifestations due to excessive copper deposition in the body.
Homologues: Orthologues: chimpanzee ATP7B (99% identical), macaque ATP7B (96% identical), rabbit ATP7B (87% identical), guinea pig ATP7B (83% identical), mouse Atp7b (83% identical), rat Atp7b (82% identical), dog ATP7B (78% identical), tropical clawed frog atp7b (66% identical), pig ATP7B (59% identical), zebrafish atp7b (54% identical), Drosophila melanogaster ATP7 (39% identical), Caenorhabditis elegans cua-1 (36% identical), and 2 more. Paralogues in human: ATP7A (57% identical), ATP2B3 (15% identical), ATP2B2 (15% identical), ATP2B1 (14% identical), ATP2B4 (14% identical), ATP1A1 (14% identical), ATP1A2 (14% identical), ATP2A2 (14% identical), ATP2A1 (14% identical), ATP1A3 (13% identical), ATP2A3 (13% identical), ATP1A4 (13% identical), and 9 more.
Diseases named in the same sentence as ATP7B in open-access papers:
ATP7B is named in the same sentence as 182 diseases in open-access papers, as found by Europe PMC text mining. Sharing a sentence is not in itself a finding about the gene and the disease. The quoted sentences say what the papers report.
Wilson disease (431 papers, 2008 to 2026). "Wilson disease (WD) is an autosomal recessive disorder caused by pathogenic variants in the ATP7B gene, leading to toxic copper accumulation." (PMID 41847123, 2026). "Wilson disease (WD) is an autosomal recessive disorder of copper transport caused by bi-allelic pathogenic variants in the ATPase copper transporting beta gene (ATP7B)." (PMID 41756680, 2026). "Wilson’s disease (WD), caused by mutations in the ATP7B gene, leads to copper accumulation and multi‐organ damage." (PMID 41523988, 2026). "Wilson disease is due to a mutation in ATP7B on an autosomal recessive pattern, which causes defective copper excretion and copper accumulation in tissues such as liver and brain." (PMID 42256941, 2026). "Wilson’s disease (WD) is an autosomal recessive disorder caused by mutations in the ATP7B gene, resulting in abnormal copper metabolism and accumulation in hepatocytes and extrahepatic organs, such as the brain and cornea." (PMID 40144630, 2025). "Wilson Disease (WD) (hepatolenticular degeneration) is a rare autosomal recessive disorder of copper metabolism characterized by a mutation in the ATP7B gene leading to copper accumulation in the brain, cornea, and liver, affecting 1 in 30,000 individuals." (PMID 41009734, 2025). "Wilson disease, a rare autosomal recessive disorder caused by mutations in the ATPase Copper Transporting Beta (ATP7B) gene, leads to impaired hepatic copper excretion." (PMID 40507673, 2025). "The specific mechanisms underlying ATP7B gene mutations and the pathogenesis of Wilson’s disease remain incompletely elucidated." (PMID 40557282, 2025). "Wilson’s disease (WD), also known as hepatolenticular degeneration, is a rare, autosomal recessive disorder caused by mutations in the ATP7B gene." (PMID 40863095, 2025). "A mutation in the ATP7B promoter region of a patient with Wilson’s disease disrupted MTF1 binding at this site, leading to the inadequate transcription of ATP7B." (PMID 40136640, 2025). "Wilson disease (WD) is an autosomal recessive disorder of copper metabolism caused by mutations in the ATP7B gene." (PMID 41472707, 2025). "Five different variants in the ATP7B gene (NM_000053.3) implicated in Wilson disease were identified in eight participants." (PMID 40679974, 2025). "For example, the HBB and HBA2 genes are associated with thalassemia, the ATP7B gene is linked to Wilson’s disease, and a specific set of genes is related to hepatocellular carcinoma." (PMID 40136557, 2025). "Hepatolenticular degeneration (OMIM: 277900), also known as Wilson’s disease (WD), is an autosomal recessive genetic disease mainly characterized by abnormal copper metabolism caused by ATP7B gene mutation, which mainly involves the liver, brain, and cornea." (PMID 40557282, 2025). "Wilson Disease (WD) is a rare genetic disorder characterized by variants of the ATP7B gene and impaired copper metabolism." (PMID 41219933, 2025). "Wilson disease (WD) is a rare autosomal recessive disorder of copper metabolism, resulting from mutations in the ATP7B gene." (PMID 41230834, 2025). "Wilson’s disease (WD) is the best-known brain mineralisation disorder and is caused by biallelic variants in ATP7B, which normally encodes a copper-transporting P-type ATPase expressed predominantly in the liver." (PMID 40649801, 2025). "In Wilson’s disease (WD), mutations in the ATP7B gene impair its function, hindering copper excretion." (PMID 40510202, 2025). "Wilson’s disease (WD) is a rare, autosomal recessive disorder resulting from mutations in the ATP7B gene, located on the long arm of chromosome 13." (PMID 41008730, 2025). "ATP7B gene, associated with Wilson disease, had a carrier frequency of in our cohort of 1:36, markedly higher than the NFE population rate of 1:50." (PMID 41303398, 2025).
Wilson disease (continued). "Wilson’s disease is an autosomal recessive illness of copper metabolism caused by a mutation in the ATP7B gene at 13q14.3, resulting in defective copper cyanoprotein production and biliary excretion." (PMID 40002122, 2025). "Wilson’s disease (WD) causes intracellular copper accumulation, due to a genetic defect in the copper-transporting protein ATP7B." (PMID 41391774, 2025). "Wilson disease is a disorder of copper (Cu) homeostasis caused by the malfunction of Cu transporter ATP7B and associated Cu accumulation in tissues." (PMID 40661833, 2025). "In this study, the four most common recessive genes of metabolism disorders were identified (> 1/60), including the SRD5A2 gene (5-alpha reductase deficiency), ATP7B gene (Wilson disease), PAH gene (Phenylketonuria), and SLC25A13 gene (Citrin deficiency)." (PMID 40447697, 2025). "Particularly Wilson’s disease (caused by pathogenic variants in ATP7B), Fabry disease (GLA), and glycine encephalopathy 1 (GLDC) were reported to have disease onset variability and late-onset cases." (PMID 41283366, 2025). "Wilson’s disease (WD) is an autosomal recessive genetic disorder characterized by impaired copper metabolism due to mutations in the ATP7B gene, which encodes a copper-transporting ATPase." (PMID 39857728, 2025). "Dysfunction in key components of this network leads to the disruption of Cu homeostasis, resulting in fatal disorders such as Wilson disease, which is caused by mutations in the hepatic Cu efflux transporter ATP7B." (PMID 39922819, 2025). "Wilson’s disease is one type of liver function injury caused by the ATP7B gene mutation, which leads to copper overload in liver cells." (PMID 41462995, 2025). "Verification of the effect of mutations in the ATP7B gene on pathogenicity can not only effectively improve the diagnosis of hepatolenticular degeneration but also provide theoretical support and research ideas for the study of other genetic diseases." (PMID 40557282, 2025). "Wilson disease (WD) is caused by mutations of the copper-transporting gene, ATP7B, leading to abnormal copper metabolism." (PMID 40384935, 2025). "Hepatolenticular Degeneration (HLD) is a copper metabolism disorder caused by mutations in the ATPase Copper Transporting Beta (ATP7B) gene that manifests primarily as liver injury and neuropsychiatric symptoms." (PMID 40438368, 2025). "Wilson’s disease (WD) is a rare autosomal recessive disorder resulting from mutations in the ATP7B gene, which is involved in copper transport." (PMID 41464699, 2025). "Genetic testing for Wilson’s disease identified a homozygous ATP7B H1069Q mutation, confirming the diagnosis." (PMID 41464699, 2025). "Wilson disease (WD) is an autosomal recessive disorder caused by mutations in the ATP7B gene, which impairs biliary copper excretion and leads to its progressive accumulation in the liver and brain." (PMID 41480142, 2025). "Wilson’s disease, on the other hand, arises from mutations in the ATP7B gene, impairing copper metabolism and leading to copper accumulation in the liver and subsequent release into the bloodstream." (PMID 40242706, 2025). "Though, as mentioned, this element is crucial for health, excessive amounts of Cu can be toxic, like we see in Wilson’s disease, which is a genetic mutation in ATP7B leading to excessive amounts of Cu in the body and, therefore, several neurological problems." (PMID 39899648, 2025). "Our analysis also identified carriers of heterozygous variants in recessive genes, including pathogenic ATP7B variants, which are associated with Wilson’s disease in a homozygous or compound heterozygous state." (PMID 41465155, 2025). "Wilson disease, caused by pathogenic variants in the ATP7B gene, was the fourth most common autosomal recessive condition in our cohort, with a 3.6% carrier frequency." (PMID 41595422, 2025).
Wilson disease (continued). "Hepatolenticular degeneration, or Wilson's disease (WD), is an autosomal recessive ailment resulting from mutations in ATP7B, which is essential for regulating copper metabolism in the body." (PMID 40557038, 2025). "For instance, mutations in the HBB and HBA2 genes are linked to thalassemia, while ATP7B mutations cause Wilson’s disease." (PMID 40136557, 2025). "Wilson’s disease is a genetic disorder caused by variants in the ATP7B gene, located on chromosome 13." (PMID 41480351, 2025). "Wilson’s disease is caused by pathogenic variants in ATP7B, a gene that is primarily expressed in the liver, brain, kidney, and placenta." (PMID 41464699, 2025). "Wilson’s disease (WD) is a rare, autosomal recessive genetic disorder resulting from mutations in the ATP7B gene." (PMID 40809427, 2025). "Wilson disease (WD) is an inherited disorder of copper metabolism caused by mutations in the ATP7B gene, leading to pathological copper deposition in the liver and other tissues." (PMID 40917366, 2025). "Wilson’s disease (WD) is an autosomal recessive genetic disorder caused by ATP7B mutations that induce impaired copper metabolism." (PMID 40552147, 2025). "Wilson disease (WD) is a hereditary condition characterized by impaired copper metabolism, resulting from mutations in the P-type ATPase ATP7B gene." (PMID 40384935, 2025). "In our patient, genetic testing for Wilson’s disease identified a homozygous ATP7B H1069Q mutation, confirming the diagnosis." (PMID 41464699, 2025). "The compound heterozygous variants (c.2145C>T and c.2304dupC) in ATP7B likely synergistically contribute to the proband’s abnormal clinical phenotype, aligning with the recessive inheritance pattern of Wilson’s disease." (PMID 40557282, 2025). "Variants in the ATP7B gene decreases intracellular transmembrane transport of copper leading to toxic copper accumulation and a disease known as Wilson disease (WD)." (PMID 39807082, 2025). "Trafficking phenotypes of Wilson disease-causing ATP7B mutants that disrupts putative ATP7B–AP1 interaction further substantiates the role of AP-1 in apical sorting of ATP7B." (PMID 38032054, 2024). "Wilson disease (WD) is an autosomal recessive metabolic disease characterized by copper metabolism disorder caused by ATP7B gene mutation." (PMID 38660222, 2024). "Wilson disease (WD) is an autosomal recessive neurodegenerative disorder affecting copper metabolism (MIM #277900) via pathogenic variants of the ATP7B gene." (PMID 39209822, 2024). "Wilson disease (WD) is a genetic disorder of copper metabolism caused by variants in the ATP7B gene." (PMID 38270718, 2024). "Genetic testing (two via Sanger sequencing, two via panel-based NGS, and one via WES) identified a heterozygous mutation in the ATP7B gene for five individuals clinically diagnosed with Wilson disease." (PMID 38510075, 2024). "Wilson’s disease (WD) is a rare, autosomal recessive disorder of copper metabolism caused by pathogenic mutations in the ATP7B gene." (PMID 39201720, 2024). "Deficiencies in ATP7B cause Wilson’s disease, which is associated with Cu toxicity due to impaired Cu export from the liver and hepatic hyperaccumulation of Cu." (PMID 38727263, 2024). "Using an adeno-associated vector (AAV) encoding human ATP7B complementary DNA (cDNA) in the hepatocytes of the Atp7b-/- Wilson disease mouse, adequate expression of ATP7B was achieved to reduce hepatic copper and prevent liver injury." (PMID 38731973, 2024). "As a copper-storing liver disease caused by inheritable malfunctioning or missing ATP7B, Wilson disease is characterized by a disturbed cellular homeostasis of copper handling primarily in the liver cell." (PMID 38928368, 2024). "Conversely, excessive copper levels in the CNS are also pernicious as demonstrated in Wilson's disease in which mutations to the copper transporter ATP7B result in abnormal CNS copper deposition and neurodegeneration." (PMID 39164165, 2024).
Wilson disease (continued). "The genetic confirmation of ATP7B mutations, coupled with the positive response to chelation therapy, strongly supports the diagnosis of Wilson Disease as the cause of the patient’s neurological and psychiatric symptoms." (PMID 38306527, 2024). "Mutations in ATP7A and ATP7B can lead to copper metabolism disorders such as Menkes disease and Wilson’s disease." (PMID 38218941, 2024). "Wilson’s disease (WD) is an autosomal recessive disorder related to copper metabolism resulting from mutations in the ATP7B gene." (PMID 39247638, 2024). "Wilson’s disease exemplifies the excessive accumulation of copper in the liver, attributable to a mutation in ATP7B." (PMID 38690269, 2024). "Wilson disease (WD) is a rare inherited autosomal recessive disorder caused by a mutation in the ATP7B gene." (PMID 39559689, 2024). "Wilson disease (WD) is an autosomal recessive disorder caused by a loss of function mutations in the ATP7B gene, which encodes for the transmembrane copper-transporter, P-type ATPase beta." (PMID 38072238, 2024). "Wilson’s disease (WD) is an example of a specific well-studied inherited disease associated a mutation in the ATPase copper transporting beta gene which encodes for a protein responsible for removing extra copper from the body." (PMID 39285928, 2024). "As a copper-storing liver disease caused by inheritable malfunctioning or missing ATP7B genes, Wilson disease is characterized by disturbed cellular homeostasis of copper handling primarily in the liver cell." (PMID 38731973, 2024). "In contrast, pathogenic variants in ATP7B lead to copper accumulation in liver, kidney and brain, leading to Wilson disease, which is characterized by liver cirrhosis and neurological symptoms." (PMID 38032054, 2024). "Mechanistic events are similar in animals or humans exposed to excessive amounts of exogenous copper compared to patients with Wilson disease, except for their ATP7B gene mutations as a basis for this specific clinical liver injury." (PMID 38731973, 2024). "Wilson’s Disease (WD) is a genetic disorder that is caused by defects in the transmembrane copper-transporting ATPase protein encoded by the ATP7B gene." (PMID 38254704, 2024). "Hepatolenticular degeneration (Wilson disease) is an autosomal recessive monogenic disorder caused by mutations in the ATPase copper transporting beta (ATP7B) gene located on human chromosome 13." (PMID 39093796, 2024). "We have trained and validated two algorithms: TabNet and XGBoost on a high-confidence dataset of manually annotated, ACMG & AMP classified variants of the ATP7B gene associated with Wilson’s Disease." (PMID 38758754, 2024). "Tsvetkov P detected an increase in HSP70 abundance in both cells using copper ionophores and in the liver of ATP7B gene-deficient mice (a mouse model for Wilson’s disease)." (PMID 38904034, 2024). "Wilson disease (WD) is a genetic disease caused by mutations in ATP7B, an ATPase responsible for the excretion of copper from the liver into bile." (PMID 38982450, 2024). "Wilson disease (WD) is an autosomal recessive disorder caused by genetic mutations in the ATP7B gene." (PMID 38939990, 2024). "Wilson’s disease (WD) is an autosomal recessive condition caused by a mutation in the ATP7B gene, encoding for a copper transporter protein (P-type ATPase), which leads to copper accumulation in the liver, kidneys, bones, brain, and eyes." (PMID 38673463, 2024). "Excess amounts of copper in these and other organs explains the broad manifestation of Wilson disease due to local ATP7B gene mutations." (PMID 38731973, 2024). "In most patients with Wilson’s disease, there are focal nonsense mutations, which are responsible for the structural changes within ATP7B membrane domains." (PMID 38248841, 2024). "Wilson disease is an autosomal recessive disorder based on variants of the ATP7B genes that encode the protein ATP7B." (PMID 38731973, 2024).